CD4 (CD4 molecule)
Diseases named in the same sentence as CD4 in open-access papers (continued):
Sharing a sentence is not in itself a finding about the gene and the disease.
tumor (continued). "This pathway involved predominantly CD8+ T cells, and, to a lesser extent, CD4+ T cells, but no other lymphoid or myeloid populations, was restricted to the tumor microenvironment and required IFNAR1 recognition." (PMID 39213189, 2024). "Furthermore, many prognostic parameters were strongly and positively interrelated, namely densities of CD4 T cells in tumor and stroma, density of CD8 T cells in stroma and distance from tumor cells to CD4 T cells." (PMID 40604303, 2024). "The most studied ligand, CCL16, has demonstrated an anti-cancer impact in mouse colon carcinoma and breast cancer through enhanced expression, attributable to an increase in CD4+ T cells, CD8+ T cells, and DC infiltration into the tumour, as well as in prostate cancer." (PMID 38339377, 2024). "Similarly, the proportion of both activated CD4+ and CD8+ T effector cells in the tumor region was higher in patients who responded to camrelizumab than in those who did not." (PMID 38448521, 2024). "A significant percentage of tumor‐infiltrating CD8+ and CD4+ T cells expressed Siglec‐10." (PMID 39373395, 2024). "In immunohistochemistry, tumor cells diffusely expressed CD45, CD56, CD4, BCL2 TdT and CD43." (PMID 39210931, 2024). "Together, these findings indicate a crucial role for vaccine-elicited CD4+ T cells recognizing tumor-specific neoantigens, but not tumor-unrelated universal antigens, in optimal immune control of the MC-38 tumor." (PMID 39040850, 2024). "CD4+ T cells, primed by MHC class II presentation on APCs, can assist CD8+ T cells, induce MHC class I expression on cancer cells, activate myeloid cell cytotoxicity, and directly kill tumor cells." (PMID 39204053, 2024). "Examples of the controls utilized in this study are Hek293 in vitro cells, HVEM untreated tumor cells, unstained CD4+ T cells, and non-malignant healthy controls." (PMID 38785930, 2024). "We speculated that dead fluke-secreted antigens might stimulate the proliferation and differentiation of CD4+ T-cells, simultaneously reducing the regulatory T-cell infiltration, which modulated the TME and was conducive to tumor control possibly." (PMID 39193390, 2024). "The expression of GSDMC was significantly and negatively correlated with the tumor purity of LIHC (p < 0.05), while it was significantly and positively correlated with the degree of infiltration of B cells, CD4+ T cells, macrophages, neutrophils and dendritic cells." (PMID 38434972, 2024). "The overexpression of prognostic onco‐lncRNAs might contribute to CD4+ T cell depletion via increased APC co‐inhibition, which primarily mediates anti‐tumor immunity by providing help for CD8+ cells." (PMID 39431755, 2024). "At the same time, there was no evident change in MB49 tumor growth, suggesting that CD4+ T cells do not restrict MB49 tumor growth." (PMID 38701369, 2024). "The absence of B2m, Jak1 and LMP2 expression on EMT6 tumor cells did not impact the infiltration of macrophages, effector CD4+ or CD8+ T cells, or CD4+ regulatory T cells (Tregs)." (PMID 38427670, 2024). "As a major CD4 + T-cell effector cytokine, IFN-γ is secreted in large quantities in localized regions of the tumor and can subsequently promote the transcription of PD-L1 in both tumor and immune cells in TME." (PMID 38898490, 2024). "The tumor-infiltrating lymphocytes (TILs) in the central and peripheral regions of the tumors were analyzed separately using markers including CD20, CD3, CD68, CD8, CD4, CD163 and FOXP3." (PMID 39198311, 2024). "To assess the capacity of our mCAR-Vβ2 T cells to target malignant T cells in vivo, we generated a patient-derived xenograft (PDX) model in NSG mice populated with total CD4 T cells from a Vβ2+ leukemic PTCL patient, or with tumor line Jurkat-TRBV20-1 (Vβ2+) cells." (PMID 38225288, 2024). "Regulating tumor fatty acids; Reducing MDSC and Treg; Increasing CD8+ T cell and CD4 + T cell." (PMID 39660124, 2024).
tumor (continued). "Consistent with the combined effect observed with APVAC1 and APVAC2, this vaccine elicited the generation of circulating polyfunctional neoantigen‐specific CD4+ and CD8+ T cell responses, enriched in a memory phenotype, and increased infiltration of T cells into the tumor." (PMID 39215399, 2024). "In tumor tissues, the percentages of CD8+ T cells, T cells CD4 memory activated, T cells gamma delta, NK cells, and Macrophages M1 were higher, while the percentages of Plasma cells, Tregs, and T cells CD4 memory resting were lower (P < 0.05)." (PMID 38383747, 2024). "The remodelling of the tumour chemokine/receptor landscape and the increased persistence of CD8+ T cells lacking Cbx3/HP1γ allows their optimum invasion into tumours at the cost of CD4+ Tregs." (PMID 39169517, 2024). "Moreover, BG/OVA@EcN exhibited the strongest ability to promote tumor infiltration of the activated IFN‐γ+CD8+ T and CD69+CD8+ T cells, as well as the activated CD69+CD4+ T cells, while decreasing the numbers of Tregs (Foxp3+CD25+CD4+CD3+CD45+ cells)." (PMID 38009498, 2024). "In order to test this hypothesis, we performed antibody-mediated CD4+ T or CD8+ T cells depletion in Ogt−/− and control tumor-bearing mice and examined the tumor growth and survival." (PMID 38168435, 2024). "Moreover, RTRT treatment resulted in a notable elevation of CD4+, CD8+ T cells, and NK cells within the tumor microenvironment, in contrast to CNRT." (PMID 39736508, 2024). "In contrast, on day 15, while AlCVCT26@D‐Gel still exerted no impact on T cell activation due to low antigenic relevance of CT26 cell‐derived vaccines to 4T1 tumors, ZCVCT26@D‐Gel significantly expanded the frequencies of tumor‐infiltrating CD8+CD3+ T cells, CD4+CD3+ T, and IFN‐γ‐secreting T cells." (PMID 38279587, 2024). "Tumor-infiltrating immune cells with CIBERSORT showed that naive B cells, memory B cells, activated CD4 memory T cells, follicular helper T cells, resting NK cells, monocytes, macrophages M0, resting mast cells, and activated mast cells had significant distinctions between the two risk subgroups." (PMID 38436027, 2024). "CD4+% cells are mainly considered as helper cells for activating CD8+effector T cells, and there is evidence that CD4+% T cells also have independent functions in promoting anti-tumor immunity." (PMID 38327747, 2024). "Using OX40LHu-CD4 (Tnfsf4)-reporter mice, we confirmed that some tumour CCR7+ DCs express OX40L, but it was not expressed by tumour cDCs or CCR7+ DCs in the dLN." (PMID 38267413, 2024). "The presence of increased numbers of immunosuppressive CD4+CD25+ regulatory T-cells and exhausted CD8+ T-cells within RCC tumors explains the efficacy of immune checkpoint inhibitors in overcoming immune tolerance of the tumor." (PMID 39516665, 2024). "Both CD4+ and CD8+ T cells showed a significantly higher expression of CCR5 and CXCR3 in tissues compared with circulating T cells, but they were both uniformly expressed in tumor-rich areas and non-tumor tissues." (PMID 38335302, 2024). "Furthermore, the study found a significant difference in the proportions of cytotoxic CD8+ and CD4+ T cells between the LGG and HGG tumor cores." (PMID 38927907, 2024). "NeoHELP-induced tumor control was dependent on the presence of CD4+ and CD8+ T cells, and neoHELP variants encoding the non-mutated, wild-type counterparts of either the CD4 or CD8 neoantigens caused reduced tumor control." (PMID 39040850, 2024). "Additionally, as effective T cells - including activated CD4 and CD8 T cells - are crucial in the tumor microenvironment, we computed their positive correlations with the TIP score." (PMID 38571962, 2024). "Nrn1 expression in murine Treg cells and non-Treg CD4+ cells from tumor infiltrates were compared to the Treg cells and non-Treg CD4+ T cells isolated from peripheral blood." (PMID 39565188, 2024).
tumor (continued). "98% of the 7AAD+ events came from PKH26 labeled cells, confirming that the observed cytotoxicity was from tumor cell death and not from effector CD4+T cells." (PMID 38891044, 2024). "However, our current chronic HS diet treatment has shown a blunting of effector anti-tumor immune responses, as evidenced by the reduced expression of cytotoxic granzyme B and IFNγ in CD8+ and CD4+T cells." (PMID 38891044, 2024). "It is worth mentioning that the administration of colchicine significantly increased the number of CD8+ cells in both the spleen and tumor tissues, whereas no obvious changes were observed in the expression of CD4+ and CD3+." (PMID 39337506, 2024). "However, in their study, checkpoint blockade also increased the amount of other tumor-infiltrating lymphocytes, including NK cells, CD8 and CD4 T cells." (PMID 38321065, 2024). "Therefore, the infiltration of helper T cells (CD4+) and cytotoxic T cells (CD8+) in tumor tissues was further investigated." (PMID 39477929, 2024). "The small degree of activation experienced by CD4+ T cells responding to B cell-presented antigen in our experiments is unlikely to fully support an effective anti-tumour response, even in a highly lymphopenic Rag2−/− environment." (PMID 38125720, 2024). "INKT cell subsets elicit heterogeneous immune responses in which anti-tumor functions appear to be primarily mediated by the CD4-negative subset." (PMID 39267746, 2024). "Thus, CD4+ T cells are an exciting actor to look at within tumor immunogenics, as they enhance the immune response of CD8+ T cells while also acting on tumor cells presenting with particular antigens." (PMID 38572312, 2024). "Of note, while the survival against the primary tumor does not depend on CD4+ T cells, the distribution and stability of circulating tumor‐specific IgG provide a protective effect against tumor re‐challenge." (PMID 38109851, 2024). "The tumor microenvironment (TME), which is primarily composed of tumor-infiltrating immune cells (TIICs), such as neutrophils, CD4+ helper T cells, CD8+ cytotoxic T cells, NK cells, and macrophages, has been identified as a critical factor influencing the progression and treatment of HCC." (PMID 39768193, 2024). "As described for CD4+ T cells, co-culture of CD8+ T cells with MOC2 or B16 tumor cells previously irradiated with 90Y-NM600 RPT indirectly enhanced the proliferation and activation of CD8+ T cells as demonstrated by increased viability and an increased secretion of IFN-γ." (PMID 39355211, 2024). "In the present model, CD4+ TCR-T are able to control tumor growth to a lesser extent, whereas CD8+ TCR-T are not." (PMID 38545119, 2024). "In ADU-S100 + anti-ISG15 treated tumors, we observed an increase in the frequency of central memory CD4+ and CD8+ T cells in addition to an increase in effector CD4+ T cell content vs. ADU-S100 treatment alone, suggestive of enhanced anti-tumor T cell activity in situ." (PMID 38312842, 2024). "In none of the subpopulations measured significant differences were found between cell proportions: Macrophages (F4/80+), Natural killer (NK), T Lymphocytes (CD3+), helper T Lymphocytes (CD4+), cytotoxic T lymphocytes (CD8+), Treg CD4+, Treg CD8+ and B (CD19+) lymphocytes within the tumor analyzed." (PMID 38576624, 2024). "Vhl status did not alter glucose consumption in isolated tumor-infiltrating CD4+ or CD8+ T cells or cancer cells enriched as CD45–." (PMID 38618956, 2024). "Consequently, there is an augmented infiltration of CD8+ T cells, CD4+ T cells, NKT cells, and NK cells into the tumor site." (PMID 39055561, 2024). "Additionally, cps treatment led to an increase in CD4+ and CD8+ T-cell infiltration into the tumor microenvironment, activation of tumor-resident T cells, and increased production of IFN-γ." (PMID 39367471, 2024). "Niche clustering and proximity analysis revealed CAFs enrichment with low MC tumor cells, while almost no CD4+ T cell distribution." (PMID 39015573, 2024).
tumor (continued). "To elucidate whether EPI correlates with T cell activation in tumor-bearing mice, we performed IHC staining for CD8+, CD4+ and CD3+ T cells in the tumors of three groups." (PMID 38622609, 2024). "However, it is technically challenging for us to investigate the stimulation of CD4+ and CD8+ T cells in vivo and its direct effect on tumor burden in Med23 knockout mice and the detailed mechanism needs to be further studied." (PMID 38195889, 2024). "Additionally, DCs produce cytokines that aid in the production and expansion of tumor‐specific CD8+ and CD4+ T cells." (PMID 39118566, 2024). "In contrast to CD8+ T cells, in response to MC38 tumor cells, CD4+ T cells of the immunized mice did not secrete any increased amounts of GzmB in response to the tumor cells when compared to those T cells of unimmunized mice T cells." (PMID 38247803, 2024). "With the increased CD4+ Tregs and effector CD4+ T cells in FLC tumor, we hypothesized that IL-10 blockade could work in FLC in conjunction with blockade of PD-1 to reactive effector CD8+ and CD4+ T cells." (PMID 38429349, 2024). "Therapeutic CCL2-blockade also decreased the recruitment of MDSCs in both the blood and tumors collected from lung cancer-bearing mice and resulted in increased CD4+ and CD8+ T cell infiltration of tumors, higher production of IFNγ, and improved survival of tumor-bearing mice." (PMID 39114657, 2024). "Activated DCs present tumor antigens on MHC I or MHC II molecules to CD8+T cells and CD4+ T cells, respectively, and the body’s antitumor immune effect is ultimately mediated by T lymphocytes (CD8+ cytotoxic T lymphocytes and CD4+ helper T cells)." (PMID 40630838, 2024). "Also, the high availability of tumor antigens stimulates the adaptive immune response by activating dendritic cells to present antigens and recruiting both virus- and tumor-specific CD4+ and CD8+ T cells to the tumor." (PMID 39594663, 2024). "Since CD4+ T cells are the primary target for MDV transformation, this increase may be due to the expansion of tumor cells." (PMID 38953352, 2024). "UA treatment in vivo did not affect the abundances of CD4+ T cells, regulatory T cells (Tregs), and NK cells while decreasing the infiltration of myeloid‐derived suppressor cells (MDSCs) in the tumor and spleen." (PMID 38447147, 2024). "Furthermore, a high proportion of infiltrating regulatory T cells (Tregs—CD3 + CD4 + CD25 + FoxP3+), and a low CD8:Treg ratio have been demonstrated to correlate with tumour size and lymph node metastases in papillary thyroid cancer." (PMID 39001359, 2024). "CD4 T cells usually do not express Nkg2d; however, a large proportion of tumor-infiltrating NKG2D+ CD4 T cells that release FAS ligands (FASL) are present in patients with tumors." (PMID 39534532, 2024). "Notably, these pre-clinical studies have shown that in tumors with the same amount of CD4+ and CD8+ T cells, those with higher 18F-AraG tumor uptake were more likely to respond to immunotherapy." (PMID 39104861, 2024). "Given the increase in B16F10 tumour-infiltrating DCs, co-stimulatory molecules on DCs, and activated (CD25+, TIGIT+) CD4 T cells, we predicted DC and T cell interactions might play a role in prolonging survival in Fgl2−/− mice." (PMID 38191799, 2024). "Inhibiting the PD-1/PD-L1 pathway can significantly boost the infiltration of CD4+ and CD8+ T cells in tumor cells, and effectively regulate the expression of a range of immune-related factors such as IL-2, IFN-γ, and TNF-α, thereby strengthening the body's anti-tumor immune function." (PMID 38312647, 2024).
tumor (continued). "Moreover, treatment with CDK4/6is also resulted in a reduction in the circulating myeloid-derived suppressor cell (MDSC) population (known as the queen bee of the tumor microenvironment) while preserving other T-cell subsets such as CD8+ and CD4+ T cells." (PMID 39593745, 2024). "Besides, TT-EV miR-5193 level was also positively correlated with the CCL21 level and the numbers of CD11c+ DCs, CD4+ T cells and CD8+ T cells in tumor tissues and the CCL21 level and DC number were also positively correlated." (PMID 38250037, 2024). "In several recent studies, OS of CCA patients was positively correlated with the infiltration of CD8+ T cells and CD4+ T cells at the tumor site, in contrast to a negative correlation with the over infiltration of activated Regulatory T Cells (Tregs)." (PMID 39766138, 2024). "Regardless of tumor sites, CD8+ T cells and activated CD4 memory T cells were associated with favorable survival, while eosinophils were the opposite." (PMID 38493212, 2024). "The ability of anti-LILRB4 to restore IL-2 production in HDVax-induced CD4+ T cells prompted us to ask whether IL-2 supplementation would restore effector CD8+ T cell function and tumour rejection." (PMID 39048822, 2024). "Treatment with rSmeg-hMIF-hIL-7, a vaccine which could induce anti-MIF immune response, enhanced activation of CD4 + and CD8 + T cells in a MC38 tumor-bearing mouse model." (PMID 38685050, 2024). "Analysis of tumor-immune infiltrations in PAC by TIMER showed that infiltration levels of macrophages, monocytes, myeloid dendritic cells (mDC), CD4 + T cells, CD8 + T cells, natural killer cells and memory B cells were positively correlated with LGI3 expression significantly." (PMID 38394487, 2024). "Elevated serum IgG3 levels in tumor-bearing mice, even in early stages without sufficient CD4 T cell help, indicate their T-cell-independent action." (PMID 39791721, 2024). "It is commonly known that CD4+ and CD8+ adaptive T cells, among others, may trigger cytotoxic responses for anti-tumor immunotherapy." (PMID 39567970, 2024). "We evaluated the B cell, T cell CD4, T cell CD8, Neutrophil, Macrophage, and DC infiltration scores of each patient in each tumor based on gene expression and we obtained six types of immune cell infiltration scores for 9406 tumor samples from 38 tumor types." (PMID 39176095, 2024). "Hypocellularity was observed in all major T cell subpopulations, with an absolute cell count normalized to the control of 56.78 ± 12.67%, 55.17 ± 12.59% and 70.68 ± 15.95% for CD8+, helper (CD4+ FOXP3−) and regulatory (CD4+ FOXP3+) T cells, respectively, on day 4 after tumor IR." (PMID 38951172, 2024). "Indeed, we observed enhanced infiltration of lymphocytes, including CD4+ and CD8+ T cells, within the tumor microenvironment following PRV treatment." (PMID 39205202, 2024). "Tumor-infiltrating lymphocytes (TILs) in the HCC encompass the group of diverse immune cells such as CD8+ T cells, CD4+ T cells, Tregs, NK cells, or B cells that affect HCC progression through compound immunological mechanisms and interactions with various cells and TME." (PMID 39408564, 2024). "When compared with tumor-bearing WT mice, CD4+ T cells, but not CD8+ T cells, obtained from tumor-bearing CD11c:DTA mice exhibited enhanced expressions of PD-1 and TIM-3 in TdLNs." (PMID 39206204, 2024). "Tumor cell-derived EVs (TEVs), on the other hand, have given rise to a novel way of antitumor vaccination, by interacting with DCs systemically and facilitating endogenous tumor antigen transfer, DC maturation, and increased CD8+ T cell recruitment, infiltration, and CD4+ T cell memory." (PMID 39030582, 2024). "The immune cell profile of immunized mice had a significantly higher number of activated T cells, as indicated by the increased frequency of CD44+CD4+ and CD44+CD8+ T cells, which have a crucial role in suppressing tumor growth, as compared to the untreated controls." (PMID 39534596, 2024).